INS (insulin)
Diseases named in the same sentence as INS in open-access papers (continued):
Sharing a sentence is not in itself a finding about the gene and the disease.
diabetes (continued). "The mean duration of diabetes was 11(±8) years and most of the respondents (62%) were on insulin or combination with insulin use regime." (PMID 37719056, 2023). "With diabetes, the body cannot produce sufficient insulin (type 1 diabetes) or cannot effectively utilize the hormone (type 2 diabetes)." (PMID 37238305, 2023). "Dulaglutide combined with insulin degludec significantly reduces glucose fluctuations in patients with type 2 diabetes mellitus and improves the TIR rate." (PMID 37255975, 2023). "Probiotics containing Bacillus subtilis have been shown to regulate insulin and HbA1c levels and ameliorate glucose tolerance and lipid profiles in an animal model of streptozotocin-induced diabetes." (PMID 37894792, 2023). "Diabetes mellitus (DM) is a persistent metabolic condition characterized by a decrease in insulin secretion or action." (PMID 38131990, 2023). "Regarding knowledge of diabetes on their type of medications 40 respondents uses insulin with oral hypoglycemic agents, 86 use oral hypoglycemic agents, 57 use insulin only and 7 uses other." (PMID 36973400, 2023). "We used comorbidities, CCI scores, insulin, number of oral antidiabetic and antihypertensive drugs as surrogate markers of diabetes severity." (PMID 37161539, 2023). "The metabolic parameters (body weight, glucose, and insulin levels) were reduced after the treatment of Mangifera indica Linn extracts in the diabetes mice model." (PMID 36909158, 2023). "Among other findings, a favorable effect of that nutrition model has been demonstrated on the values of glycated hemoglobin, glucose, insulin, or other metabolic parameters in diabetes patients." (PMID 36771207, 2023). "Diabetes mellitus (DM), a metabolic disorder characterized by disturbances in glucose metabolism by insulin deficit/resistance and chronic hyperglycaemia, is a significant threat to global health." (PMID 37686143, 2023). "Currently, the MiniMed 780G system is the most advanced insulin pump system approved for the treatment of people with type 1 diabetes mellitus (T1DM) aged from 7 to 80 years." (PMID 37845757, 2023). "We also stratified participants based on diabetes type and performed linear regression analysis with adjustment for age, sex, diabetes duration, and percentage of participants on insulin to see if the study findings would change in each subgroup." (PMID 37194402, 2023). "This study investigated eight different characteristics of the subjects, including the number of pregnancies, plasma glucose level, diastolic blood pressure, sebum thickness, insulin level, body mass index, diabetes pedigree function, and age." (PMID 36983587, 2023). "Higher glucose levels and abnormalities in insulin production characterize diabetes mellitus (DM), or insulin resistance, and some people can have both." (PMID 38202711, 2023). "T2D, which makes up 90% of all diabetes cases, involves disruptions in whole-body glucose homeostasis due to resistance of peripheral tissue to insulin and decreased insulin production by pancreatic β-cells." (PMID 37886432, 2023). "The ADA algorithm for combined injectable therapy in type 2 diabetes mellitus changed in 2017, in which basal insulin along with GLP-1 RA was preferred compared to basal plus rapid-acting insulin or two daily doses of premix insulin." (PMID 36650625, 2023). "Diabetes mellitus (DM) is a chronic condition characterized by high blood glucose level (hyperglycemia) due to the body’s inability to properly produce or use insulin." (PMID 36986847, 2023). "Increasing the knowledge of patients about their drugs, insulin administration, and diabetes complications improves self-care behaviors and medical adherence." (PMID 38098964, 2023). "All patients were treated with the basal-bolus regimen before insulin pump therapy, with an average number of injections per day of 4.3 ± 0.5 injections per day (corresponding to intensified diabetes treatment)." (PMID 37185052, 2023).
diabetes (continued). "Diabetes is a metabolic disease involving defective insulin action, inadequate insulin secretion, or both, resulting in chronic hyperglycemia and disturbances in carbohydrate, fat, and protein metabolism." (PMID 37765360, 2023). "When diabetes is induced, morphological abnormalities of islets within pancreatic tissue and a decrease in insulin secretion have been identified." (PMID 37623224, 2023). "This activity restricts the absorption of fat, inhibits fat accumulation, reduces body weight, and improves insulin sensitivity, thus preventing or delaying the progression from prediabetes to diabetes." (PMID 38099180, 2023). "Patients with TyG index ≥ 8.47 had higher levels of TC, LDL-C, TG, FPG, DBP, and BMI, a lower level of HDL-C, and a higher proportion of drinker, diabetes mellitus, oral hypoglycemic agents and insulin use, compared to patients with TyG index < 8.47." (PMID 37660027, 2023). "Individuals with elevated TyG index demonstrated an increased occurrence of diabetes, insulin therapy, and diabetes as the primary factor leading to ESRD." (PMID 37891651, 2023). "Insulin is the most common drug used in the clinical treatment of diabetes, so insulin overdose is mostly an accidental treatment for diabetic patients, including the miscalculation of dosage and incorrect use of insulin specifications." (PMID 38250973, 2023). "Type 2 diabetes mellitus (T2DM) is characterized by insulin resistance and a relative deficiency of insulin." (PMID 37100872, 2023). "This review aims to highlight the main characteristics of each Automated Insulin Delivery (AID) system available for patients affected by Type 1 Diabetes Mellitus." (PMID 36983941, 2023). "We recently described an approach to detecting significant anti‐insulin antibodies in exogenous insulin‐naïve participants, and now adapt this to insulin‐treated diabetes." (PMID 37562398, 2023). "Predictive capabilities of blood glucose levels hours holds potential for augmenting current closed-loop insulin controllers for diabetes management, if our findings hold true for diabetic patients." (PMID 37169738, 2023). "A combination of HDAC inhibitors and transient insulin treatment corrects epigenetic alterations in bone marrow-derived hematopoietic cells of the pancreas and thymus, leading to diabetes remission in the STZ model." (PMID 37311905, 2023). "Nevertheless, it seems that the decline in insulin levels is more gradual in WS1 diabetes compared to T1DM." (PMID 36835101, 2023). "Diabetes mellitus (DM) is a metabolic disease with a marked increase in blood glucose due to impaired insulin secretion or impaired insulin function." (PMID 37333473, 2023). "As the patients with the diabetes require to take the blood glucose lowering drugs or to inject the insulin to the body for avoiding the occurrence of the diabetes complications, monitoring the blood glucose values is of the great importance to the diabetes." (PMID 36999925, 2023). "Diabetes etiology involves abnormalities in the functioning of pancreatic beta cells, insulin sensitivity in peripheral tissues, and the regulatory mechanisms that control glucose metabolism." (PMID 38283440, 2023). "Mitochondrial dysfunction has been found to be an important factor affecting β-cell sensitivity to insulin, and impaired mitochondrial oxidation, reduced biogenesis, and excessive ROS production are common features of diabetes." (PMID 36979626, 2023). "This was followed by insulin pump data (39% [36/93] ranked in the top 3), communication with the diabetes team between visits (37% [34/93] ranked in the top 3), and laboratory test results (37% [34/93] ranked in the top 3) as useful features." (PMID 37440296, 2023). "Observed differences in BMI are expected, as diabetic patients tend to have higher BMI than healthy subjects, and differences in insulin and metformin use are in line with the duration of diabetes and metabolic control in diabetic patients." (PMID 37883447, 2023).
diabetes (continued). "Insulin is the most important treatment for diabetes, so all people with type 1 diabetes and half of the patients with type 2 diabetes should use insulin." (PMID 37828117, 2023). "KEGG pathway analysis indicated that the pyroptosis-related hub genes were enriched in maturity-onset diabetes of the young, insulin secretion, type 1 diabetes mellitus, and glutamatergic synapses." (PMID 36967805, 2023). "Most of these metabolites (flavonoids, m-coumaric acid, p-coumaric acid, quercetin, gallic acid) are known to boost insulin sensitivity, slow down the rate, digestion and absorption of sugar, hence supporting their protective effects in diabetes." (PMID 37089941, 2023). "The early stage of diabetes development involves a compensatory phase marked by insulin resistance, increased insulin production, and an enlarged β-cell mass." (PMID 38115080, 2023). "Clinical studies have identified abnormal electrocardiogram (ECG) changes during severe hypoglycemia in patients with insulin-treated diabetes, including QT interval prolongation, abnormal T-wave morphology, bradycardia, and other cardiac arrhythmias." (PMID 37200277, 2023). "Among those identified with type 2 diabetes mellitus, attaining typical blood glucose levels necessitates the use of oral hypoglycemic agents or insulin." (PMID 38202676, 2023). "The lutein-rich PSPL supplementation restored the FBG, sodium, chloride, ALP, and insulin levels within the normal range in diabetes-induced rats." (PMID 37274105, 2023). "The mean diabetes duration was 7.3 ± 2.6 years and mean time on insulin pump therapy (AHCL system) was 1.87 ± 0.7 years in the study population." (PMID 38057844, 2023). "There was no clear relationship between vitamin E supplementation and HbA1c fasting glucose, insulin concentrations, and various blood lipid parameters in diabetes mellitus patients." (PMID 37571239, 2023). "Our results provide evidence of the protective effect of higher childhood BMI on insulin secretion and sensitivity, which are crucial intermediate diabetes traits." (PMID 37280435, 2023). "Even though diabetes mellitus has been known for centuries and insulin-based treatment has been widely accepted and applied as a standard treatment, the control of glucose levels in diabetes-affected patients still remains a challenge." (PMID 36986620, 2023). "Type 1 diabetes mellitus (T1D) is one of the most frequent chronic diseases in children; it is due to an autoimmune destruction of the insulin-producing β-cells in the islets of Langerhans within the pancreas." (PMID 37468976, 2023). "The ECHO Diabetes team helped to solidify a plan to give her rapid-acting insulin after she completed meals, which prevented over-bolusing and significantly reduced the rates of severe hypoglycemia after meals." (PMID 37535407, 2023). "During the current decade, there has been several innovations in the management of diabetes, including insulin pumps improvement." (PMID 37616289, 2023). "Management of diabetes with insulin lowers plasma TAG by returning LPL activity to the normal level." (PMID 37970378, 2023). "Blood flow within the islet microcirculation holds significance for islet development and the regulation of the islet hormone network, with microcirculatory abnormalities impeding insulin production and accelerating the progression of diabetes." (PMID 38111575, 2023). "In a randomized controlled trial, 87 pregnant women with GDM or type 2 diabetes mellitus (T2DM) received insulin detemir (n=42) or NPH (n=45), with short-acting insulin aspart as needed." (PMID 37775682, 2023). "The two nutritional treatments seem to exhibit similar efficiency in improving insulin resistance and fasting hyperinsulinemia, which are crucial pathologic processes for developing diabetes, while improving β-cell function and endogenous insulin clearance." (PMID 36837859, 2023).
diabetes (continued). "Vitamin C (50 mg/kg) with naringin co-treatment improved insulin concentration and oxidative stress reduction in rats with streptozotocin-induced diabetes." (PMID 37570594, 2023). "Treatment with insulin in type 2 diabetes mellitus and lipid-lowering measures, such as dietary changes or pharmacologic interventions such as statins, restores LDL catabolism and improves endothelial function." (PMID 37238983, 2023). "Diabetes can be efficiently treated with curcumin by increasing insulin resistance and decreasing leptin, resistin, and insulin levels." (PMID 37240220, 2023). "Patients with cystic fibrosis have less insulin secretion and are more likely to have diabetes and require insulin therapy." (PMID 37242426, 2023). "Inhibition of ceramide synthesis can improve insulin sensitivity and prevent obesity-induced diabetes." (PMID 38027178, 2023). "For example, the anticorrelation between the 1st frequency component in 8G and percent insulin secreted in 8.3G/QLA separates the classical inbred, wild-derived, and diabetes-susceptible strains into distinct groups despite the variability in the trait." (PMID 37787501, 2023). "One of the most widespread metabolic diseases, Type-2 Diabetes Mellitus (T2DM) is defined by high blood sugar levels brought on by decreased insulin secretion, reduced insulin action, or both." (PMID 37936909, 2023). "Altered insulin sensitivity–like insulin resistance in liver, adipose and other insulin target tissues–can lead to pancreatic β cell failure and promote the pathogenesis of type 2 diabetes mellitus (T2DM) in humans." (PMID 36730473, 2023). "L-Arg supplementation was also shown to reduce adiposity and improve insulin sensitivity in animal models of obesity as well as in patients with diabetes and obesity." (PMID 37072850, 2023). "The benefits of exercise training on insulin signaling have been emphasized by experimental and clinical studies showing a 60% reduction in diabetes diagnosis as a result of regular exercise in individuals at high risk." (PMID 37508000, 2023). "Diabetes, a chronic metabolic disorder, is characterized by persistent hyperglycemia resulting from insufficient insulin production, impaired insulin action, or both." (PMID 37893045, 2023). "CGM data were downloaded proactively every 2 weeks from computer cloud-based device accounts of 146 individuals with diabetes on multiple daily insulin injections or insulin pump therapy." (PMID 37629520, 2023). "The study proposes cost optimization through diabetes and insulin management through smartphone devices." (PMID 36778554, 2023). "Multiple mechanisms including hyperglycemia and decreased signaling by Wnt, adipokine, insulin, or Igf1 have been proposed to impair osteoblast differentiation and function in diabetes, but their functional relevance in vivo remains elusive." (PMID 37144869, 2023). "The structured self-monitoring blood glucose (SMBG) (at least four fingerpicks per day) together with reinforced patient-centered education remains the first-line glucose monitoring strategy for adults with diabetes on intensive insulin therapy." (PMID 37676398, 2023). "Some recent immunological studies in insulin-requiring young-onset diabetes individuals have been conducted at or close to diagnosis." (PMID 36778553, 2023). "Patients with T1D often have impairments in their counter-regulatory response to hypoglycaemia as well as insulin secretion, particularly if the duration of diabetes is long." (PMID 37685946, 2023). "This study aimed to determine the feasibility and acceptance of the group diabetes insulin self-management education (DIME) programme for people with T2D who are starting insulin." (PMID 37237318, 2023). "The sample was limited by a lack of cultural diversity, though broadly representative of the Australian population with diabetes in respect of age, but with a slightly lower prevalence of insulin use." (PMID 37903137, 2023).
diabetes (continued). "Almost all of the patients 229 (99.1%) received counseling during the diagnosis of diabetes and 201 (87%) received all of the advice related to diabetes and insulin." (PMID 37759193, 2023). "Patients with T1D are prone to require lifelong comprehensive management, which includes insulin therapy, metabolic monitoring, nutritional guidance, diabetes education, lifestyle management, and psychosocial care." (PMID 37064701, 2023). "This paradigm shift from episodic self-monitoring and manual insulin dosing to continuous, real-time monitoring and automated insulin delivery has the potential to revolutionize diabetes management." (PMID 38239544, 2023). "In this context, functional beta-cell deficiency results in an inability to secrete enough insulin to compensate for the effects of FOXO1, resulting in diabetes." (PMID 36902173, 2023). "High dietary iron and dysregulated iron metabolism are risk factors for type 2 diabetes mellitus (T2DM), affecting most of its features of decreased insulin secretion, insulin resistance and increased hepatic gluconeogenesis." (PMID 36978919, 2023). "Vitamin D levels are inversely associated with the risk of diabetes, and vitamin D supplementation leads to improvements in glucose and insulin levels and prevents evolution to diabetes among people with prediabetes." (PMID 37764829, 2023). "Adult patients with diabetes who switched their basal insulin to insulin degludec were included and evaluated for its impact on insulin doses, hemoglobin A1c (HbA1c), hypoglycemic events, and/or body weight changes during a 90-day follow-up period." (PMID 36601214, 2023). "We examined various variables related to diabetes treatment, including medications, such as metformin and injectable insulin, as well as diabetes duration." (PMID 37893143, 2023). "The potential mechanisms include diabetes, hypertension, insulin resistance and direct cellular effects such as inflammatory, lipotoxic and hemodynamic factors." (PMID 37883495, 2023). "Diabetes is a chronic disease resulting from insufficient insulin production by the pancreas or ineffective insulin use by the body." (PMID 37957549, 2023). "Recently, Singh demonstrated a QD-based aptasensor with aptamer functionality, which was used to detect insulin in diabetes patients’ serum samples." (PMID 37232930, 2023). "In the United States, where the prevalence of diabetes now exceeds 10%, more than 7 million people require insulin therapy." (PMID 37971985, 2023). "Type 2 diabetes mellitus (T2D) is a metabolic disorder characterized by decreased insulin secretion and sensitivity and corresponds to 90% of all cases of diabetes." (PMID 37858161, 2023). "We performed a systematic review and meta-analysis of randomized controlled trials (RCT) data comparing Once-Weekly Insulin Icodec and Once-Daily Insulin Glargine U100 in patients with type 2 diabetes mellitus." (PMID 37249450, 2023). "These found that of American Indian and Alaska Native patients diagnosed with diabetes before age 30 years and taking insulin alone or with oral medications, 36.9% (90 of 244) developed any new DR within 4 years." (PMID 36892822, 2023). "Type 2 diabetes (T2D), which is characterized by defective peripheral tissue responsiveness to insulin (insulin resistance, IR) and β cell dysfunction, accounts for ~90% of all diabetes cases." (PMID 37583355, 2023). "Impaired awareness of hypoglycemia (IAH) is common in insulin-treated patients with diabetes and correlates with the duration of insulin treatment." (PMID 37298308, 2023). "Mean duration of diabetes was 95.18±54.49 months and mean duration of insulin use was 6.45±3.7 years." (PMID 36694770, 2023). "Plenty of evidence is now available supporting the role of the protein kinase phosphatase receptor (RPTPs) in the signaling and secretion of insulin, and consequently, in IR conditions up to type 2 diabetes mellitus." (PMID 37298967, 2023).